STAT3 (signal transducer and activator of transcription 3)
Diseases named in the same sentence as STAT3 in open-access papers (continued):
Sharing a sentence is not in itself a finding about the gene and the disease.
glioma (continued). "Previous study has shown STAT3 inhibition overcomes TMZ resistance by reducing MGMT expression in glioma." (PMID 34291563, 2021). "Accordingly, expanded monocytes bear markers of immune suppression, such as p-STAT3, and of immune dysfunction, like PD-L1, highlighting their involvement in the immune derangement process in gliomas." (PMID 35069595, 2021). "The administration of a STAT3 pharmacological inhibitor attenuated the infiltration of monocytes into glioma." (PMID 34503167, 2021). "CYB561D2 up-regulation induces immunosuppression and aggression via activating STAT3 in gliomas and CYB561D2 mediates ROS-tumor immunity crosstalk." (PMID 34372858, 2021). "Similar to miRNAs, lncRNAs can also serve as target genes of STAT3 in gliomas and undergo transcriptional regulation." (PMID 34425834, 2021). "Several studies, in mice models of glioma and on patient-extracted glioma tumor cells, have demonstrated the benefits of inhibiting STAT3 that enhances the anti-tumor immune response by improving T cell, DCs and NK activation in the TME." (PMID 34440802, 2021). "Overall, these results indicated that β-elemene suppressed the activation of STAT3 pathway through elevated ROS production in glioma cells." (PMID 34257541, 2021). "In summary, we show that CYB561D2 up-regulation induces immunosuppression and aggression via activating STAT3 in gliomas." (PMID 34372858, 2021). "In glioma, miR-124 can enhance T cell-mediated immune clearance and modulate T helper cell differentiation by inhibiting the STAT3 signalling pathway." (PMID 34425834, 2021). "Glioma cell lines possessed similar response patterns to SD‐36 but different responses to the STAT3 inhibitor Stattic." (PMID 34291563, 2021). "In a model of glioma, CD9-enriched EVs derived from endothelial cells also enhance glioma stem cell tumorigenesis by activating the BMX/STAT3 axis." (PMID 33738282, 2021). "In this review, we analysed the noncoding RNAs that regulates the expression of STAT3 and that are regulated by STAT3 in gliomas." (PMID 34425834, 2021). "To this end, we utilized Stattic, a specific p-STAT3 inhibitor, to suppress the activation of STAT3 in glioma cells." (PMID 33576874, 2021). "Serving as a vital ceRNA, CRNDE activates the PIWIL4/STAT3 signaling pathway through miR-384, which further accelerates the proliferative and invasive capacities of glioma cells." (PMID 34729101, 2021). "We detected the effect of NC on JAK2/STAT3 signaling by western blot analysis of related proteins in NC‐treated glioma cells." (PMID 33788424, 2021). "STAT3 is upregulated in PTEN-mut but not in the PTEN-wt subgroup (PTEN-mut vs. Normal, PTEN-wt vs. Normal), showing STAT3 is correlated with PTEN-mut glioma." (PMID 34336645, 2021). "LncRNAs CASC9 and miR155HG promote STAT3 through the ceRNA mechanism, and STAT3, in turn, acts as a transcription factor in the nucleus of glioma cells to promote the expression of CASC9 and miR155HG." (PMID 34425834, 2021). "To further support that CYB561D2 activates STAT3 in glioma tissues, we measured STAT3 protein levels in the same samples of gliomas (n = 35) and analyzed its correlation with CYB561D2." (PMID 34372858, 2021). "It was found that exposure of glioma cells to IL-6 (50 ng/ml) increased the expression of p-STAT3, while co-incubation of β-elemene abolished such activation." (PMID 34257541, 2021). "Gliomas often overexpress phosphorylated signal transducer and activator of transcription 3 (p-STAT3) that induces a variety of immunosuppressive factors including IL-10, prostaglandin E2 (PGE2), vascular endothelial growth factor (VEGF) and TGF-β." (PMID 34765554, 2021). "Recently, ERK1/2 and STAT3 signaling pathways have also been reported to play critical roles in glioma invasiveness." (PMID 34503167, 2021). "Continuous activation of STAT3 in GBM with PTEN loss can induce cell proliferation, anti-apoptosis, maintenance of glioma stem cells, tumor invasion, angiogenesis, and immune evasion." (PMID 34336645, 2021).
glioma (continued). "In 2019, a study reported that ELTD1 facilitates proliferation, migration, and invasion in glioma by activating the signaling axis JAK/STAT3/HIF–1α." (PMID 34068040, 2021). "The experimental results exhibited that NC treatment inhibited the expression of JAK2, p‐JAK2, STAT3, and p‐STAT3 in glioma cells, and these inhibitory effects increased with increasing NC concentration." (PMID 33788424, 2021). "Taken together, these data support that H2O2 induced CYB561D2 produced more ascorbate which further activated STAT3 in glioma cells." (PMID 34372858, 2021). "Several recently published meta-analyses have suggested that the expression levels of STAT3 and p-STAT3 are promising prognostic biomarkers for glioma, breast, lung, and colorectal carcinoma." (PMID 34789292, 2021). "In summary, our results show that fraxetin inhibits proliferation, invasion, and migration of glioma by inhibiting JAK2/STAT3 signaling and inducing apoptosis of glioma cells." (PMID 33959183, 2021). "Studies have shown that STAT3 signaling was capable of modulating mesenchymal transformation of gliomas." (PMID 34745848, 2021). "MiRNA clusters let-7a-1 ~ let-7d (including let-7d, let-7f-1 and let-7a-1) can directly target and inhibit STAT3 to promote apoptosis and autophagy of glioma cells." (PMID 34425834, 2021). "Here, we provide a detailed characterization of CYB561D2 in gliomas and our results suggest that CYB561D2 up-regulation induces immunosuppression and aggression via activating STAT3 in gliomas." (PMID 34372858, 2021). "Some transcriptional factors with well-recognized functions in embryonic development, such as Nanog, Oct4, Sox2, STAT3, have been identified as oncogenic drivers which can affect the fate of glioma stem cells and regulation of glioma development." (PMID 34408983, 2021). "RNAi-mediated knockdown of STAT3 in human U251 glioma cells led to increased apoptosis via the suppression of transcriptional downstream targets of STAT3, such as Bcl-xL, Mcl-1, and survivin." (PMID 33498872, 2021). "Using a large cohort of clinical glioma samples and patient-derived GSCs, we established the association between CD109 and STAT3 phosphorylation." (PMID 33986188, 2021). "Both Dp44mT and bovine lactoferrin, as iron chelators, suppress growth, migration, and EMT process of glioma by inhibiting IL-6/STAT3 signaling pathway." (PMID 34568059, 2021). "NC also inhibited relevant glioma stem‐like cell‐related markers through its effects on the JAK2/STAT3 pathway." (PMID 33788424, 2021). "Aberrant activation of STAT3 is often observed in numerous human malignancies, including MM, leukemias, lymphomas, breast, ovary, melanoma, glioma, head and neck, liver, and kidney cancers." (PMID 34771643, 2021). "Signaling through MAPKs, Akt, STAT3 are known to play important role in various cell functions in gliomas, such as cell proliferation, angiogenesis, apoptosis, inflammation, oncogenesis, and differentiation." (PMID 34408983, 2021). "Data from PLA demonstrated that oxelaidin suppresses interactions between RRAD and EGFR or STAT3 in glioblastoma cells, supporting its utility as an active anti-glioma agent." (PMID 33980886, 2021). "One study showed that paeoniflorin triggered cell growth inhibition and apoptosis via the enhancement of STAT3 degradation in glioma cells." (PMID 33531900, 2021). "The cooperation of NF-κB and Stat3 recruitment regulates the radiation-induced invasion and migration in glioma." (PMID 35052701, 2021). "LINC00662 acts as an oncogene, promoting the development of glioma by blocking the miR-340-5p/STAT3 axis." (PMID 37305396, 2021). "The STAT3 inhibitor can target the central nervous system tumor by induing immunocyte tumor homing in a CXCL10-dependent manner." (PMID 34603309, 2021). "Our bioinformatic analysis showed that STAT3 mRNA expression significantly correlated with M2 macrophage infiltration in glioma and GBM." (PMID 32483429, 2020).
glioma (continued). "Taken together, the miR cluster MC‐let‐7a‐1 ~ let‐7d promotes glioma cell autophagy and apoptosis by repressing STAT3." (PMID 31868319, 2020). "According to clinical information from datasets, STAT3 mRNA expression was inversely related to overall survival in glioma patients." (PMID 32483429, 2020). "Activation of STAT3 in glioma cells is closely correlated with poor clinical prognoses in patients with grade III glioma." (PMID 32256354, 2020). "As more data emerge regarding its interaction with Wnt, RANK, STAT3, and other signal cascades or tumorigenic molecules, it is becoming clear that curcumin has the potential to have in vivo anti-glioma effects." (PMID 33322413, 2020). "Next, we validated the efficacy of ACT001 in prolonging survival by affecting the STAT3-PD-L1 axis in a murine glioma model." (PMID 32483429, 2020). "Western blotting, RT-PCR and immunofluorescence were used to detect PD-L1 and p-STAT3 expression in glioma cells exposed to ACT001." (PMID 32483429, 2020). "IHC staining of 53 tissue samples confirmed that relatively high phosphorylated STAT3 and PD-L1 protein expression was associated with a relatively advanced World Health Organization (WHO) glioma grade." (PMID 32483429, 2020). "The results of subgroup analysis further emphasize the importance and effectiveness of standard treatment and it also highlights the potential of STAT3/p-STAT3 for the development of valuable prognostic biomarkers and therapeutic agents of glioma." (PMID 33299498, 2020). "Microarray data analysis provided data indicating the involvement of miR cluster MC‐let‐7a‐1 ~ let‐7d in glioma via STAT3." (PMID 31868319, 2020). "Targeting FAK/STAT3 sensitizes gliomas to the anti-EGFR agent gefitinib and alkylating agent temozolomide in human gliomas." (PMID 32045997, 2020). "hnRNPA2/B1 has been reported to mediate the pathogenesis of gliomas via the classic STAT3 and AKT-related signaling pathways." (PMID 32463472, 2020). "Leptin released from glioma cells partially contributes to angiogenesis, as evaluated by induced tube formation capacity in human umbilical vein endothelial cells (HUVECs) via STAT3 phosphorylation." (PMID 33316976, 2020). "Initially, the present study detected the down‐regulation of let‐7d, let‐7a‐1, and let‐7f‐1 in glioma, which was accompanied by the up‐regulation of STAT3." (PMID 31868319, 2020). "It should be noted that PTP1B plays a critical role in down-regulation of activated STAT3 in glioma cells." (PMID 32517717, 2020). "Combines with radiotherapy to disrupt tumor growth and mainly disrupts glioma stem cells by inhibiting bone marrow and X-linked (BMX)/STAT3 activation." (PMID 32872659, 2020). "This is consistent with glioma database analyses showing that ETNPPL expression is inversely correlated to STAT3 and MKI67 whose expression are higher in foci and glioblastomas." (PMID 32218467, 2020). "In TNF-α/IL-6/sIL-6R treated glioma cells, STAT3 can be phosphorylated (p-STAT3) as a transcription factor to participate in IL-6 signaling." (PMID 33227992, 2020). "Another study demonstrated that overexpression of circ-HIPK3 promoted proliferative and invasive capacities of glioma cells by sponging miR-124-3p up-regulating STAT3 level." (PMID 32061256, 2020). "Our results confirmed that STAT3 bound to PD-L1 promoter and modulated PD-L1 transcription in glioma cells." (PMID 32483429, 2020). "In our knowledge, this study is the most comprehensive assessment of the trials regarding STAT3/p-STAT3 expression and glioma prognosis to date." (PMID 33299498, 2020). "Accordingly, in PTEN-deficient GBM, the inhibition of STAT3 allows the expression of CXCL8 gene that promotes proliferation, invasion and spreading of glioma cells." (PMID 33066172, 2020). "The JAK/STAT3 axis plays an essential role in promoting tumor initiation and radio-resistance in glioma CSCs." (PMID 33390934, 2020).
glioma (continued). "Functional studies demonstrate that ACYP2 acts as an oncogenic function in glioma cells through regulating intracellular Ca2+ homeostasis and subsequently activating c-Myc and STAT3 signals." (PMID 32517717, 2020). "In our previous study, STAT3 levels correlated significantly with the clinico-pathological grade of glioma." (PMID 32045997, 2020). "In glioma cells, PA decreased p-STAT3 in the attached cells, and we also observed that PA decreased STAT3 activation in the attached MDA-MB-231 cells, which was attenuated by the expression of active STAT3 along with an increase in survivin." (PMID 33182770, 2020). "It was shown recently, that miR cluster MC-let-7a-1 ~ let-7d promotes glioma cell autophagy and apoptosis by repressing signal transducer and activator of transcription 3 (STAT3)." (PMID 32138249, 2020). "This will lead to decreased activity of calpain and subsequent activation of c-Myc and STAT3, thereby promoting malignant phenotypes of glioma cells." (PMID 32517717, 2020). "The level of total STAT3 and phosphorylated STAT3 decreased also when ADV-infected glioma cells were transfected with MYD88 siRNA." (PMID 32843056, 2020). "Concurrently, we detected the expression of STAT3 between the three types of glioma tissues and the adjacent normal tissues by RT‐qPCR." (PMID 31868319, 2020). "In glioma cells, GALNT7 was co-expressed with several gene including STAT3 which was associated with the JAK-STAT signaling pathway, PVR which participated in the CAMs pathway." (PMID 32308562, 2020). "Western blotting showed that the level of MYD88, STAT3 and phosphorylated STAT3 increased in primary glioma cells after ADV infection." (PMID 32843056, 2020). "Collectively, these data suggest that the inhibition of hnRNPA2/B1 can reduce the growth of gliomas through STAT3 and AKT signaling pathways, and this inhibition is expected to be a therapeutic target for gliomas." (PMID 32463472, 2020). "For instance, interferon inhibited proliferation of glioma stem cells and their sphere-forming capacity and induced STAT3 activation." (PMID 32488114, 2020). "Our data indicate the potential clinical value of treatment with VEGF or STAT3 inhibitors in glioma patients expressing low levels of PDCD4." (PMID 33304903, 2020). "The results indicated that STAT3 mRNA was significantly correlated with M2 macrophage infiltration in glioma and GBM." (PMID 32483429, 2020). "CD9, an early fusion molecule, stabilizes gp130 by preventing its ubiquitin‐dependent lysosomal degradation to promote STAT3 activation in glioma stem cells." (PMID 31837208, 2020). "Currently, many studies showed that STAT3, as an oncogene, promotes tumor progression in a variety of malignant tumors, including glioma." (PMID 32457836, 2020). "Together with IL6, IL10 and FGF are also known to activate STAT3, which was found to be constitutively activated in glioma." (PMID 33153019, 2020). "A recent study has provided a proof that the expression of miR-21 is modulated by β-catenin/STAT3 pathway and facilitates glioma cell invasion." (PMID 32231463, 2020). "With P < 0.05 as the statistical threshold, STAT3 was highly expressed in metastatic glioma cells, which also indicated the accuracy and application prospect of single-cell sequencing research." (PMID 33198677, 2020). "Further studies with larger sample sizes and multicenter/countries are needed to shed more light on the more precise correlation between STAT3/p-STAT3 and glioma." (PMID 33299498, 2020). "STAT3 mRNA was inversely related to tumor purity and positively related to the immune score in both glioma and GBM datasets." (PMID 32483429, 2020). "The oncogenic role of STAT3 in gliomas is consistent with the observation that STAT3 activation is rarely detected in normal brain tissue." (PMID 33371351, 2020). "Signal transducer and activator of transcription 3 (STAT3) has been reported to be aberrantly activated in gliomas, and be identified as a potential therapeutic target." (PMID 32517717, 2020).
glioma (continued). "We found a substantial increase in p-STAT3 in both the glioma cells expressing IL-33 and the Iba1+ cells, a result consistent with a bidirectional signaling between the glioma cells and the Iba1+ TAM." (PMID 33020472, 2020). "The key findings demonstrated that MC‐let‐7 targets STAT3 and down‐regulates its expression, which ultimately hinders glioma cell proliferation and stimulates the apoptosis and autophagy." (PMID 31868319, 2020). "A series of in vitro and in vivo functional studies demonstrate that ACYP2 is a potent oncogene in glioma cells through promoting Ca2+ efflux and subsequently activating c-Myc and STAT3 signals." (PMID 32517717, 2020). "SH3GL2, as a suppressor for tumors, and has reduced expression in glioma tissues promoting migration and infiltration of glioma cells by enhancing STAT3/MMP2 signaling." (PMID 32328342, 2020). "To understand the role of STAT3 mRNA expression in glioma immune system interactions, we examined the correlations between STAT3 mRNA and immune-related markers." (PMID 32483429, 2020). "In central nervous system cancer cell lines, compounds nakiterpiosin and cucurbitacin I had a positive correlation coefficient greater than 0.3 (higher expression of STAT3 related to resistance)." (PMID 32486001, 2020). "In this study, the authors find that, in glioma, a STAT3-mediated expression signature can stratify patients for targeted precision therapy." (PMID 31399589, 2019). "STAT3 effects in gliomas have been suggested to depend on STAT5b activity possibly attributed to their close proximity in chromosome 17q." (PMID 31698775, 2019). "For example, the PDGFRβ-targeted aptamer chimera bearing the siRNA to STAT3 reduced glioma cell viability, tumor growth, and angiogenesis in a subcutaneous model of glioma." (PMID 30644073, 2019). "Although it is well known that STAT3 is upregulated in glioma and plays a role in tumor progression and survival, little is known about STAT6 in this context." (PMID 31530290, 2019). "STAT3 has also been shown to regulate the self-renewal potential of glioma cells, suggesting that its inhibition would lead to a more curative and sustained outcome." (PMID 31399589, 2019). "Evidence also abound that STAT3 signaling plays a role in maintaining the self-renewal capabilities and multilineage differentiation potential of glioma stem cells (GSMs)." (PMID 31783691, 2019). "Study also indicated that miR-124 works through the inhibition of STAT3 signal to enhance the T cell mediated clearance of glioma cells." (PMID 31032345, 2019). "In this study, we identified STAT3-high to describe a cohort of both glioma and GBM patients who had poorer prognosis." (PMID 31399589, 2019). "To test the therapeutic potential of LPP-formulated siRNA in vitro and in vivo, we selected Stat3 as a target because it is frequently overactivated in glioma and also hard-to-drug." (PMID 30857197, 2019). "Here we investigated the therapeutic potential of intracranially applied LPP containing Stat3-specific siRNA in an orthotopic Tu2449 glioma model." (PMID 30857197, 2019). "Selective targeting of STAT3 for glioma treatment remains one of the current challenges, especially due to lack of representative in vitro and in vivo models of tumor heterogeneity." (PMID 31698775, 2019). "In gliomas, miR-124 is poorly expressed but upregulation of its expression in glioma cancer stem cells inhibited the STAT3 pathway." (PMID 31557897, 2019). "We demonstrate that the LPP-mediated delivery of siRNA mediates efficient knockdown of Stat3, suppresses Stat3 activity and limits cell growth in murine (Tu2449) and human (U87, Mz18) glioma cells in vitro." (PMID 30857197, 2019). "The expression of p-STAT3 was negatively correlated with AP-2α expression in glioma samples, in which p-STAT3 expression was observed together with low AP-2α expression (Fisher's exact test, P<0.001)." (PMID 31534499, 2019).